SPDYE15 (speedy/RINGO cell cycle regulator family member E15)
Synonyms: SPDYE15P
Tractability: No criterion of Open Targets' tractability assessment is met for any kind of drug.
Gene: Protein-coding gene on chromosome 7 (75,335,343 to 75,345,396, forward strand). Ensembl gene ENSG00000286014.
Gene Ontology:
Molecular function: protein kinase binding
Homologues: Orthologues: rat Spdye4 (49% identical), mouse Spdye4a (48% identical), mouse Spdye4b (44% identical). Paralogues in human: SPDYE13 (100% identical), SPDYE14 (100% identical), SPDYE10 (99% identical), SPDYE11 (99% identical), SPDYE17 (99% identical), SPDYE8 (99% identical), SPDYE9 (99% identical), SPDYE12 (99% identical), SPDYE3 (88% identical), SPDYE18 (84% identical), SPDYE16 (83% identical), SPDYE2 (83% identical), and 6 more.